NOTCH1 (notch receptor 1)
Diseases named in the same sentence as NOTCH1 in open-access papers (continued):
Sharing a sentence is not in itself a finding about the gene and the disease.
gastric cancer (continued). "This suggested that Notch1 signaling plays an important role in the carcinogenesis and the maintenance of CD133 positive diffuse type gastric cancers." (PMID 27489358, 2016). "In this study, we aimed to clarify the clinicopathological significance and the prognostic and predictive value of NOTCH1 and NOTCH2 expression in gastric cancer (GC)." (PMID 25954607, 2015). "In this study, we first aimed to clarify the role of NOTCH1 and NOTCH2 protein expression in gastric carcinomas relative to prognosis and to the clinico-pathological characteristics of patients not treated by chemotherapy." (PMID 25954607, 2015). "Conversely, co-transfection of Notch1 inhibitors in P-MSCs with CSF2 knockdown showed rescued the inhibitory effect of CSF inhibitors, including augmented tropism towards gastric cancer cells, enhanced expression of FAP and α-SMA, elevated expression of inflammatory factors GM-CSF, FGF, and PDGF-BB." (PMID 37865637, 2023). "A meta-analysis of 15 studies containing 1547 gastric cancer cases and 450 controls from the MEDLINE, EMBASE, and Chinese National Knowledge Infrastructure (CNKI) databases revealed that the expression of Notch1 and Notch2 was significantly higher in tumor tissues of GC compared to normal tissues." (PMID 36768307, 2023). "Thus, we explored the anti-tumor effect of DOP on gastric cancer cells by converting M2 into M1 subtype macrophage polarization via STAT6/PPAR-r and JAGGED1/NOTCH1 signaling pathways, as a result, DOP reduces apoptosis and prevents migration in gastric cancer." (PMID 37894541, 2023). "The inhibition of gastric cancer cell proliferation, migration, and drug resistance by the supernatant from P-MSCs with CSF2 knockdown was also enhanced by Notch1 co-inhibition." (PMID 37865637, 2023). "In addition, luteolin impaired HIF-1α/VEGF and Notch1-VEGF signaling in melanoma and gastric cancer individually." (PMID 35784750, 2022). "In recent years, it has been shown that circRNAs can influence tumor cell resistance by enhancing EMT; for example, circ_001680 and circ-NOTCH1 are elevated in colorectal cancer (CRC) and gastric cancer (GC), respectively, and both these circRNAs can promote cancer stem cell (CSC) expansion via EMT." (PMID 35615158, 2022). "The co-culture of macrophages and stomach-cancer cells MKN45 and BGC823 could enhance cell proliferation accompanied by the activation of Notch1/Notch2 signaling and upregulation of DLL3." (PMID 35382168, 2022). "Furthermore, studies have indicated that the activation of Notch1, Notch4, and DLL4 is crucial in the initiation and progression of gastric cancer." (PMID 35846998, 2022). "In view of cell stemness regulation by Reck by suppressing Notch1 shedding and activation in gastric cancer, we tested the expression changes of Reck and Notch1 in A549 cells with or without overexpression of miR-221/222." (PMID 33959615, 2021). "Our data demonstrated that 4-BR and the JNK inhibitor inhibited Notch1 expression, suggesting that 4-BR may contribute to JNK-mediated gastric cancer stemness regulation." (PMID 35723384, 2021). "A study undertaken by Piazzi and colleagues to assess the role of Notch1 and the corresponding ligand Dll1 in gastric carcinoma shows that Dll1 is not detected in KATOIII, SNU601, SNU719 and AGS cells from eight different types of gastric cancer cell lines." (PMID 28881855, 2017). "Similarly, using another gastric cancer stem cell marker, CD44, Notch1 and Hes1 were found to be highly expressed in gastric cancer stem-like cells (GCSCs)of MKN45 cells." (PMID 28881855, 2017). "Similarly, only poorly-differentiated gastric cancer cell lines expressed CD133 and activated-Notch1." (PMID 27489358, 2016).
gastric cancer (continued). "Since both N1ICD and CD133 were co-expressed in poorly-differentiated gastric cancer cell lines, we hypothesized that CD133 expression is induced by Notch1 signaling." (PMID 27489358, 2016). "Here, we report that CD44+ gastric cancer stem-like cells (GCSCs) showed enhanced proliferation capacity compared to their CD44− counterparts, and this proliferation was accompanied by the high expression of Notch-1 (in vitro)." (PMID 23710217, 2013). "In gastric cancer, a previous study indicated that the activation of Notch-1 promotes disease progression, and the expression of Notch-1 was significantly higher in cancer cells than in normal tissues." (PMID 23710217, 2013). "In this study, we showed that Notch1 could regulate CDH5 expression by targeting CDH5 promotor, providing insight into how Notch1 upregulation enhanced the proliferation, migration, invasion, and vasculogenic mimicry capacity of gastric cancer cells." (PMID 39172098, 2024). "To date, there have been no reports on whether DOP inhibits gastric cancer by regulating macrophage polarization and the associated mechanism involving the JAGGED1/NOTCH1 signaling pathway." (PMID 37894541, 2023). "Circ_001680 and circ-NOTCH1 are increased in colorectal cancer (CRC) and gastric cancer (GC), respectively." (PMID 32171304, 2020). "Moreover, in the examinations of gastric cancer cells, Luteolin resulted in the inhibition of vasculogenic mimicry formed by Hs-746T gastric cancer cells and found that a dramatic decrease in the VEGF secretion of Hs-746T cells resulted from the inhibition of Notch1 expression in gastric cancer." (PMID 36992138, 2023). "However, whether or not Notch1 mRNA has a prognostic role in gastric cancer patients remains elusive." (PMID 27363496, 2016).
hepatocellular carcinoma (94 papers, 2011 to 2026). A malignant tumor that arises from hepatocytes. "Upregulated Ncstn expression reportedly promotes hepatocellular carcinoma cell growth and metastasis via β-catenin activation in a Notch1-dependent manner, while its mutation disrupts the development of hair follicles." (PMID 39703504, 2024). "In this study, we observed that Notch1 was associated with the malignant behavior of hepatocellular carcinoma by analyzing the protein expression by IHC in the carcinoma specimens." (PMID 27705934, 2017). "This study was conducted to explore the role of Notch1 in the development of VM in hepatocellular carcinoma and its underlying mechanisms." (PMID 27705934, 2017). "Further, curcumin downregulated Notch-1 and caused hepatoma cells to undergo apoptosis." (PMID 39507759, 2024). "Our data demonstrate that HBX can upregulate IL-7R via NF-κB and Notch1 pathways to facilitate the activation of intracellular pathways and expression of associated molecules, and contribute to proliferation and migration of hepatoma cells." (PMID 27821177, 2016). "Interestingly, recent studies showed that HBV X protein activated Notch signaling via Notch1/Notch4/Dll4 in HBV-associated hepatocellular carcinoma." (PMID 27800305, 2016). "NCSTN promotes the growth and metastasis of hepatocellular carcinoma cells by activating β-catenin in a Notch1/AKT-dependent manner." (PMID 41472131, 2025). "Xuanfu HT can increase sorafenib sensitivity of hepatocellular carcinoma cells by antagonizing the Notch1 pathway through quercetin-binding HIF-2α." (PMID 40444091, 2025). "Another study uncovered the critical role of TET3-mediated DNA hydroxymethylation of ZMIZ1, a mechanism that activates the Notch1/c-Myc axis, alters macrophage polarization status, and ultimately affects hepatocellular carcinoma progression." (PMID 41299461, 2025). "As a result, it can inhibit the activation of Notch1 pathway and suppresses cell proliferation, migration, invasion, and angiogenesis, thus increasing the sorafenib sensitivity of hepatocellular carcinoma cells." (PMID 40444091, 2025). "In hepatocellular carcinoma, overexpression of miR-760 downregulates the expression of Notch1 and Hes1, increasing the sensitivity of tumor cells to the chemotherapeutic drug doxorubicin." (PMID 40755759, 2025). "Notch1 signaling exhibits controversial roles in hepatoma carcinogenesis, playing either oncogenic or tumor-suppressive functions." (PMID 39766289, 2024). "ZMIZ1 collaborates with Notch1 to activate c-Myc transcription and promotes M2 polarization in Kupffer cells, thereby enhancing hepatocellular carcinoma transformation." (PMID 38866828, 2024). "Previous studies have shown that SNRPA promotes an EMT-like process in hepatocellular carcinoma cells by activating the NOTCH1/Snail pathway, thereby accelerating metastasis." (PMID 39845190, 2024). "For instance, CircSEC62 accelerates microvascular invasion via activating NOTCH1/Snail pathway in hepatocellular carcinoma (HCC)." (PMID 37264406, 2023). "DHM can downregulate Notch1 expression and decrease the Bcl-2/Bax ratio in hepatoma cell lines QGY7701 and HepG2 in a time- and dose-dependent manner, inhibiting the proliferation of hepatoma cells." (PMID 35884547, 2022). "Co-operatively, Notch 1 and reactive oxygen species increase the level of Snail protein in hepatoma cells via induction of phosphorinositide 3- Kinase/Akt signaling pathway." (PMID 36374927, 2022). "We demonstrated that activation of Notch1 was significantly elevated in the livers of hepatocellular carcinoma (HCC) in Farnesoid X receptor-knockout (FXR-KO) mice and that FXR expression negatively correlated with Notch1 level during chronic liver injury." (PMID 33845903, 2021).
hepatocellular carcinoma (continued). "The current study has shown that Notch1 helps promote HBV X protein-induced hepatocellular carcinoma through the Wnt/β-catenin pathway." (PMID 34988028, 2021). "HIF-1α upregulated the expression of Notch1, Notch3 and Notch4 via binding to the hypoxia response elements in their promoter regions in hepatocellular carcinoma cell lines." (PMID 34988077, 2021). "The bioactive compounds ginsenoside Rb1 and ginsenoside Rd inhibit the development of hepatocellular carcinoma by inhibiting the activation of NOTCH1 signal." (PMID 32963562, 2020). "According to a previous research, miR-760 develops a drug-resistant function via impairing doxorubicin resistance in hepatocellular carcinoma by controlling Notch1/Hes1-PTEN/Akt signaling pathway." (PMID 31693728, 2019). "Notch 1 triggers EMT in hepatocellular carcinoma and promotes VM, while Notch4 is highly expressed in melanoma CSCs, where it promotes metastasis via the TWIST/VE-cadherin/E-cadherin pathway." (PMID 29112161, 2017). "Collectively, these findings suggest that targeting Notch1 has important therapeutic value in hepatocellular carcinoma." (PMID 27167202, 2016). "The role of NF-κB and Notch1 pathways in HBX-mediated expression of IL-7R in hepatoma cells was examined." (PMID 27821177, 2016). "First, we explored the activation of NF-κB and Notch1 pathways by measuring the phosphorylation levels of the p65 protein, as well as the levels of Notch1, in control and hepatoma cells stably transfected with HBX." (PMID 27821177, 2016). "In a limited number of tumor types, including human hepatocellular carcinoma and small cell lung cancer, NOTCH1 plays an antiproliferative role." (PMID 25149541, 2014). "This study was conducted to evaluate the effect of mesenchymal stem cells (MSCs) and a novel curcumin derivative (NCD) on HepG2 cells (hepatoma cell line) and to investigate their effect on Notch1 signaling pathway target genes." (PMID 24024180, 2013). "The present work aimed at evaluating the tumor suppressive effects of MSCs and a novel water soluble curcumin derivative (NCD) on Notch1 signaling in HepG2 cells (hepatoma cell line)." (PMID 24024180, 2013). "Ahn and colleagues found that Notch1 and Notch4 are markers for poor prognoses during hepatocellular carcinoma." (PMID 24386256, 2013). "It has been reported that aberrant expression of Notch3 is found in many hepatocellular carcinoma cells, as frequently as that of Notch1." (PMID 21673954, 2011). "In hepatocellular carcinoma, hypomethylation of the promoter region of KK-LC-1 (a cancer/testis antigen) leads to its upregulation, which in turn promotes tumor progression by activating the Notch1/Hes1 signaling pathway." (PMID 40755759, 2025). "Inhibition of NOTCH1 signaling pathway may inhibit the development of HBx-induced hepatocellular carcinoma, and NOTCH1 may become a therapeutic target for hepatocellular carcinoma." (PMID 32963562, 2020). "Moreover, it has been reported that Notch1 controls PTEN expression in hepatocellular carcinoma: the abrogation of Notch1 by siRNA approach increases PTEN expression and phosphorylation, with inhibition of both AKT and FAK activity." (PMID 28848709, 2017). "Moreover, we observed Notch1 was associated with the EMT and malignant behavior of hepatocellular carcinoma by analyzing clinical specimens, models for in vitro and in vivo experiments." (PMID 27705934, 2017). "Previously we have shown that XN reduces Notch1 in pancreas and hepatocellular cancer." (PMID 29152142, 2017). "Based on these reports, we speculated that HBX may activate NF-κB and/or Notch 1 pathway to drive IL-7R expression in hepatoma cells." (PMID 27821177, 2016).
hepatocellular carcinoma (continued). "APs may modulate immunity by activating the toll-like receptor 4 (TLR4)–mediated myeloid differentiation primary response 88 (MyD88)–dependent signaling pathway and induce apoptosis in human hepatocellular carcinoma cells by decreasing the expression of Notch1." (PMID 38466979, 2024). "Jin and his colleagues observed that MCUR1 (Mitochondrial Calcium Uniporter Regulator 1) is up-regulated in hepatocellular carcinoma (HCC) which promotes EMT by activating ROS/Notch1/Nrf2 pathways." (PMID 31766246, 2019). "YTHDF1 promotes cancer stem cell renewal and resistance to tyrosine kinase inhibitors in hepatocellular carcinoma (HCC), which enhances the stability and translation of m6A-modified NOTCH1 mRNA, leading to increased expression of NOTCH1 target genes." (PMID 39185313, 2024). "NCSTN can affect the Notch1 and AKT signaling pathways and is involved in the development of hepatocellular carcinoma." (PMID 37691920, 2023). "In hepatocellular carcinoma (HCC), higher expression of TACE/ADAM17 and Notch1 was found to predict a worse prognosis." (PMID 36226253, 2022). "In addition, our recent study has demonstrated that PAB blocks hepatocellular carcinoma (HCC) cells proliferation and invasion through inhibiting Notch1/Akt signaling pathway." (PMID 36439797, 2022). "We further showed that selenite can inhibit Notch1 expression in cultured MCF7 breast adenocarcinoma cells and HEPG2 liver carcinoma cells." (PMID 33802299, 2021). "A previous study by our group also confirmed that the up-regulation of Notch1 promotes EMT and further induces VM formation in hepatocellular carcinoma." (PMID 33549061, 2021). "It has been reported that abnormal activation of Notch signal is related to the metastasis of hepatocellular carcinoma, and NOTCH1 can activate RNF187 promoter to promote the invasion and metastasis of hepatocellular carcinoma." (PMID 32963562, 2020). "Furthermore, in hepatocellular carcinoma (HCC), CAFs secrete high levels of IL-6, which promoted stem cell-like properties in HCC cells by activating Notch 1 signalling through STAT3 Tyr705 phosphorylation." (PMID 32575680, 2020). "In conclusion, we determined that Notch1 regulates the JNK signaling pathway and increases apoptosis in hepatocellular carcinoma." (PMID 28507277, 2017). "In the present study, the expression of Notch1 and NICD1 was detected in hepatocellular carcinoma (HCC) tissues using in-vitro assays." (PMID 28507277, 2017). "The activation of NF-κB pathways and expression of Notch1 were increased in hepatoma cells transfected with HBX, and inhibition of NF-κB and Notch1 pathways significantly decreased HBX-mediated expression of IL-7R." (PMID 27821177, 2016). "Among them, there are several genes, which mediate the inhibition of miR-34a induced metastasis in human malignances, such as Notch1 and JAG1 in cervical carcinoma and choriocarcinoma cells and c-Met in in human hepatocellular carcinoma cells." (PMID 22457788, 2012). "Moreover, a link of IKKα-mediated FOXA2 phosphorylation to hepatocellular carcinoma tumorigenesis was supported by higher levels of IKKα, phosphorylated FOXA2, and activated Notch1 in hepatocellular carcinoma specimens respect to normal liver tissues." (PMID 30154786, 2018). "In fact, in some specific types of tumours such as skin cancer, small cell lung cancer or hepatocellular carcinoma, contradictory data indicate that NOTCH1 signalling could be playing anti-proliferative rather than oncogenic roles." (PMID 31605148, 2020). "Pin1 has been implicated in colorectal cancer (β-catenin), breast cancer (Cyclin D, AP-1, Akt, centrosome duplication, Notch1), prostate cancer (TRK-fused gene [TFG]), glioblastoma (NF-κB), hepatocellular carcinoma (HCC, p70S6K, β-catenin) and acute myeloid leukemia (AML, AP-1)." (PMID 25588053, 2015). "In hepatocellular carcinoma, DLL4/Notch1 generally drives tumor growth, whereas Jag1/Notch2 tends to suppress tumor progression." (PMID 41588437, 2026).
hepatocellular carcinoma (continued). "We found out that Notch1 was expressed in the non-tumor liver of rats that developed HCC while it was not expressed in the liver of rats that did not develop hepatocellular carcinoma, suggesting that the lack of Notch1 protein expression could prevent HCC development." (PMID 27167202, 2016). "In addition, in a human hepatocellular carcinoma mouse model using GFP-labeled MHCC97-H cells, an ethnopharmacologically used Celastrus orbiculatus extract containing 11 terpenes, of which the effective component is not yet known, reduces VM formation by targeting Notch1 signaling." (PMID 29112161, 2017).